CXCL12 (C-X-C motif chemokine ligand 12)
Diseases named in the same sentence as CXCL12 in open-access papers (continued):
Sharing a sentence is not in itself a finding about the gene and the disease.
viral infection (17 papers, 2010 to 2025). "These differential responses (including transcripts encoding CCL1, CCL6, CXCL11, and CXCL12) not only vary minimally with age at inoculation, the differential responses themselves are minimal, demonstrating at most 2-fold induction in response to virus infection." (PMID 21078159, 2010). "The Cxcl12-Cxcr4 axis is a well-characterized signaling pathway with pleiotropic roles in immune responses, viral infections, and cancer." (PMID 40612507, 2025). "Previously, we showed that IL-3 protects against primary viral infection by promoting the recruitment of pDCs into the lungs in a CXCL12-dependent manner." (PMID 36911737, 2023). "Correspondingly, in myxozoan-infected fish, CXCL12 was up-regulated, but following viral infection the gene was down-regulated." (PMID 36296170, 2022). "The actions of this enzyme serve to reduce the local concentration of CXCL12/SDF-1 and thereby protect the host cells from viral infection." (PMID 33339432, 2020). "Strong IFN signaling responses observed in acute viral infection are often accompanied by induction of genes associated with cell stress (DDIT3/CHOP), apoptosis (PMAIP1/Noxa), and general inflammatory chemokines (CXCL10, CXCL12, and CCL5)." (PMID 38440980, 2024). "Recent evidence has emerged implicating chemokines, specifically CXCR4 and CXCL12, as important mediators of neurogenesis; thus, chemokines produced during viral infections may influence neural precursor cell function and therefore influence recovery and repair." (PMID 20686655, 2010). "CXCL12 and CXCL13 are two well-documented B cell chemoattractants, and detection of CXCL12 and CXCL13 levels in BALF after viral infection revealed that CXCL13 expression at 3-5 d.p.i." (PMID 34868067, 2021). "Additionally, secretion of CXCL12 into culture medium was inhibited by infection with HCMV, whereas mRNA expression of CXCL12 was unaffected by viral infection in SGHPL-4 cells." (PMID 23116176, 2012). "In our SARS-CoV-2 infected iPSC-derived acinar cells, we believe CXCL12 could be playing either pro-inflammatory roles since other known pro-inflammatory transcription factors were also upregulated, such as NKFB1 and STAT3, or a defensive anti-inflammatory defensive to viral infection." (PMID 34282405, 2021).
bone cancer (16 papers, 2013 to 2024). A primary or metastatic malignant neoplasm affecting the bone or articular cartilage. "The CXCR4 and its ligand CXCL12 are known to regulate the trafficking of various immune suppressive cells to the bone tumor microenvironment, thus contributing to the disease progression and therapy resistance." (PMID 37996444, 2023). "The fact that intratumor CXCL12 production actively interferes with cancer progression is further supported by previous findings in breast and bone cancer." (PMID 34834449, 2021). "A single intrathecal injection of a CXCL12 neutralizing antibody (10 μg/10 μl) at day 10 after TCI transiently reversed bone cancer pain in a dose-dependent manner." (PMID 24735601, 2014). "It is becoming clear that CXCL12 is produced from activated astrocytes via JNK pathway on bone cancer status." (PMID 24735601, 2014). "We showed that fluorocitrate, which disrupts astrocytes function, exerted a profound blockade of CXCL12 induction in bone cancer states." (PMID 24735601, 2014). "As expected, we further found that prolonged treatment of CXCL12 neutralizing antibody in the early phase of bone cancer markedly delayed the onset of BCP behavior." (PMID 24735601, 2014). "CXCR4 expression is also enhanced in bone tumors, suggesting that CXCL12/CXCR4 signaling contributing to bone tumor growth in Akt1 transfected DU145 cells." (PMID 23902739, 2013). "CXCL12/CXCR4 signaling pathway activates sensitized neurons, astrocytes and microglia through mitogen-activated protein kinase (MAPK), promotes the release of inflammatory factors, such as IL(interleukin) and TNF, and causes persistent bone cancer pain." (PMID 39654896, 2024). "Thus, to determine the role of PI4KA in CXCL12/CXCR4 signaling contributing to bone tumor growth, we have developed stable knockdown of PI4KA in PC3-CXCR4 and C4-2B cell with two independent PI4KA shRNA (#27 and #30) through lentiviral transduction." (PMID 37996444, 2023). "Moreover, some authors have observed an increase in CXCL12 in the spinal cord in bone cancer pain and in antiretroviral toxic neuropathy." (PMID 25789329, 2015). "Bone colonizing PC-3 cells induce the expression of active MMP-9 at earlier time periods suggesting that CXCL12/CXCR4-mediated homing of PC cells to bone would functionally link with the expression of MMP-9 in local bone tumor microenvironment and induce invasive bone tumor growth." (PMID 24472670, 2014). "However, whether CXCL12/CXCR4 signals contribute to pain hypersensitivity in the state of bone cancer is still largely unexplored." (PMID 39641645, 2024). "However, it remains largely unknown whether the CXCL12/CXCR4 signaling contributes to pain hypersensitivity in a bone cancer state." (PMID 24735601, 2014). "We thus hypothesized that, in bone cancer state (especially in the early phase), CXCL12 is produced in DRG nociceptive neurons that innervate the tumor-bearing limb, and in turn axonally transported to the surface layers of SCDH where it may be released locally." (PMID 24735601, 2014). "Taken together, these results demonstrate that CXCL12/CXCR4 signaling contributed to the development and maintenance of bone cancer pain via sensitizing neurons and activating astrocytes and microglia." (PMID 24735601, 2014). "In this study, we investigated the specific cellular mechanisms of CXCL12/CXCR4 chemokine signaling in the development and maintenance of bone cancer pain after tumor cell implantation (TCI)." (PMID 24735601, 2014). "However, whether CXCL12 contributes to bone cancer pain depends on behavioral examination." (PMID 24735601, 2014). "This find indicated that CXCL12/CXCR4 signaling may be making major contributions to nociceptive signal processing by mediating glial-neuronal and glial-glial communication on bone cancer state." (PMID 24735601, 2014).
bone cancer (continued). "In addition, we recently found that epidermal growth factor receptor family members are activated downstream of CXCL12/CXCR4 signaling, providing proliferative signals in bone tumor growth." (PMID 23902739, 2013). "However, GFAP was not activated until day 7, suggesting that CXCL12 may be also produced and released from other cells in the early phase of bone cancer." (PMID 24735601, 2014).
fibrosis (16 papers, 2014 to 2024). the formation of excess fibrous connective tissue in an organ or tissue in a reparative or reactive process. "The mRNAs encoding fibronectin (Fn1), another important ECM component, and C-X-C motif chemokine ligand 12 (Cxcl12), a fibrosis-associated chemokine, were also increased by BLM administration and FBP was able to downregulate the expression of these mRNAs." (PMID 31509566, 2019). "CXCL12 can also play an inflammatory role, has been demonstrated as being involved in tissue fibrosis." (PMID 39492831, 2024). "Another author showed that the number of fibrocytes increases in the lungs and attracted to the lungs in response to CXCL12 and are involved in fibrosis in IPF." (PMID 33218322, 2020). "The promoting effect of CXCL12 on ICT during development is consistent with the recognized role of CXCL12/CXCR4 axis in adult fibrosis." (PMID 29222527, 2017). "Moreover, neutralizing anti-CXCL12 antibodies resulted in reduced recruitment of circulating fibrocytes to the injured lung and attenuated fibrosis." (PMID 27309347, 2016). "Fibrosis in AS mice treated with PBS, CXCL12, AMD3100, or CXCL12 plus AMD3100 were each significantly different from their respective sham controls (p = 0.004, p = 0.004, p = 0.005, and p = 0.005, respectively)." (PMID 28345002, 2017). "We have previously demonstrated that Ccl3−/− and Ccr5−/− mice exhibit reduction in BLM-induced fibrosis and the number of CD45+Col-I+CCR5+ fibrocytes in the lungs, together with suppressed CXCL12 expression." (PMID 29203799, 2017). "CXCR4, the receptor for CXCL12, a chemokine expressed by inflamed biliary epithelium in primary biliary cirrhosis and HCV, was enriched in portal compared to parenchymal regions in HCV patients with advanced fibrosis." (PMID 27309850, 2016).
inflammatory bowel disease (16 papers, 2008 to 2026). A spectrum of small and large bowel inflammatory diseases of unknown etiology. "In Gnai2−/− mice developing spontaneous inflammatory bowel disease, gut-derived T cells from Rgs1−/− mice displayed increased chemotaxis to CXCL12, suggesting that the balance between expression of Gαi2 and RGS1 in gut T cells may control their retention within the gastrointestinal mucosa." (PMID 27804980, 2016). "DNA microarray studies by Watanabe and co-workers demonstrated significant up-regulation of the CXCR6 motif in ulcerative colitis patients, whilst other work has indicated that the CXCL12/CXCR4 interaction is involved in several inflammatory conditions, including inflammatory bowel disease." (PMID 19555476, 2009).
oral squamous cell carcinoma (16 papers, 2009 to 2024). "The CXCL12/CXCR4 pathway can recruit macrophages in oral squamous cell carcinoma through cancer-associated fibroblast (CAF) to promote the transformation of cancer stem cells." (PMID 36308553, 2023). "The CXCL12/CXCR4 system also facilitates lymph node metastatic potential in oral squamous cell carcinoma by enabling EMT69." (PMID 29743718, 2018). "The CXCL12/CXCR4 axis plays a pivotal role in the progression of various malignancies, including oral squamous cell carcinoma (OSCC)." (PMID 36300800, 2023). "The goal of the present study was to investigate alterations of CXCL12/CXCR4 in oral premalignant lesions and oral squamous cell carcinoma (OSCC)." (PMID 22496601, 2012). "We have demonstrated that the stromal cell-derived factor-1 (SDF-1; CXCL12)/CXCR4 system is involved in the establishment of lymph node metastasis in oral squamous cell carcinoma (SCC)." (PMID 19671192, 2009).
renal cell carcinoma (16 papers, 2006 to 2025). "First, 4E-BP1 was phosphorylated in a CXCL12-dependent manner similar to the time frame reported in renal cell carcinoma." (PMID 31106142, 2019). "By staining for CXCL12 and αSMA, we showed that plasma cell accumulations often colocalized with CXCL12+ fibroblasts near TLS, supporting the evidence of renal cell cancer." (PMID 38629072, 2024). "Cells from renal cell carcinoma (RCC) tissue in the dataset GSE167573 showed tumorous samples to have multiple exonic regions in several genes, among them SPP1 or ‘ENSG00000118785’ with five exons, S100A4 with two exons and CXCL12 with five exons." (PMID 39857756, 2025). "In contrast, studies in VHL-related renal cell carcinoma and retinal hemangioblastoma high levels of CXCR4 and VEGF, and not CXCL12, were found." (PMID 26920352, 2016).
type 2 diabetes (16 papers, 2012 to 2025). "C-X-C motif chemokine 12 (CXCL12), also known as stromal cell-derived factor 1 (SDF-1), is intimately linked to the development of type 2 diabetes and associated consequences." (PMID 36582230, 2022). "CXCL12/SDF-1 has been reported both as a stimulator and an antagonist of several perspectives of inflammatory response in type 2 diabetes and its complications and CXCL12/SDF-1might be a promising treatment target to improve islet engraftment." (PMID 36714563, 2022). "We provide evidence for a distinctive cytokine induction in skeletal muscle of men with type 2 diabetes and highlight CXCL12 as an exerkine promoting skeletal muscle development and growth." (PMID 36070371, 2022). "We identified CXCL12 as an exerkine released in the circulation after exercise and with enhanced mRNA induction in individuals with type 2 diabetes in skeletal muscle." (PMID 36070371, 2022). "The chemokine CXCL12 was particularly dysregulated in skeletal muscle from individuals with type 2 diabetes, and exposure of cultured muscle cells to this exerkine directly triggered signaling events affecting proliferation and differentiation." (PMID 36070371, 2022). "According to previous reports, during early or late diabetic nephropathy, glomerular podocytes can secrete CXCL12, and inhibition of CXCL12 can significantly reduce glomerulosclerosis and proteinuria in patients with type 2 diabetes." (PMID 35510354, 2022). "Moreover, we identify CXCL12 as a plausible exerkine and mediator of skeletal muscle adaptation to exercise in individuals with type 2 diabetes." (PMID 36070371, 2022). "CXCL12 is a chemokine; thus, its local production in skeletal muscle from individuals with type 2 diabetes may be related to the attraction of neutrophils, monocytes, and lymphocytes to the tissue." (PMID 36070371, 2022). "Considering our data and evidence from mouse models, the induction of CXCL12 in skeletal muscle from individuals with type 2 diabetes is therefore likely a beneficial response, promoting local muscle stem cell recruitment and activation, leading to skeletal muscle remodeling." (PMID 36070371, 2022). "We selected 14 disallowed genes for analysis based on their identification in 2 independent studies (C1qbp, Cd302, Cxcl12, Igfbp4, Ldha, Lmo4, Maf, Oat, Pdgfra, Slc16a1, and Smad3) and/or other criteria including up-regulation in type 2 diabetes (Acot7, Ldha, and Pdgfra)." (PMID 26038943, 2015). "The transcriptomic response, and in particular the production of exerkines responsive to hypoxia, such as CXCL2 and CXCL12, suggests that the exercise-induced inflammation signature in individuals with type 2 diabetes may arise from insufficient local oxygenation of working skeletal muscle." (PMID 36070371, 2022). "The immune cells infiltrating skeletal muscle in individuals with type 2 diabetes are therefore not likely attracted by CXCL12." (PMID 36070371, 2022).
cholangiocarcinoma (15 papers, 2013 to 2026). A carcinoma that arises from the intrahepatic biliary tree (intrahepatic cholangiocarcinoma) or from the junction, or adjacent to the junction, of the right and left hepatic ducts (hilar cholangiocarcinoma). "CXCL12/CXCR4 signaling promotes cholangiocarcinoma progression and metastasis via the canonical Wnt pathway, and Wnt5a is a critical mediator of human and murine T cell CXCL12/CXCR4 signaling and migration." (PMID 28380463, 2017). "Treatment of cholangiocarcinoma cell lines with PI3K inhibitor (LY294002) or the MEK 1/2 (UO126) attenuated the effect of CXCL12-induced cholangiocarcinoma cell invasion." (PMID 26161813, 2015). "Similarly, stromal cell-derived factor-1 (CXCL12), an ECM secreted factor, has been found to play a role in promoting cholangiocarcinoma cell migration and invasion." (PMID 31687002, 2019).
diabetic nephropathy (15 papers, 2015 to 2025). "A study on the mouse model of T2D revealed that CXCL12 contributes to glomerulosclerosis, podocyte loss, and albuminuria, implicating the pathogenic role of CXCL12 in diabetic nephropathy." (PMID 26300887, 2015). "Plasma VEGF-C, VEGF-D, and CXCL-12 levels is of great value for early diagnosis and assessment of diabetic kidney disease severity." (PMID 40772333, 2025). "This study aims to investigate whether plasma levels of VEGF-C, VEGF-D, and CXCL-12 can reflect the severity of diabetic kidney disease (DKD), and to evaluate their potential as biomarkers for disease monitoring." (PMID 40772333, 2025). "Although CXCL12 is considered as one of the major mediators involved in kidney repair after ischemic acute renal failure, data regarding the role of this chemokine in diabetic nephropathy are limited." (PMID 26300887, 2015). "Increasing evidences showed that CXCL12 participated in the progression of various kidney diseases, such as AKI, diabetic kidney disease, and lupus nephritis." (PMID 39492831, 2024).
injury (15 papers, 2013 to 2025). Damage inflicted on the body as the direct or indirect result of an external force, with or without disruption of structural continuity. "Our studies and those of our peers showed that chemokine C-X-C motif ligand 12 (CXCL12) is markedly increased in the DRG after induction of neuropathic pain by nerve injury or a chemotherapeutic agent." (PMID 33658516, 2021). "We confirmed that in a prophylactic setting, this reduction was mediated by the inhibition of CCL2 and CCL12 production and the partial inhibition of CXCL12 production, which are stimulated by lung injuries." (PMID 24507087, 2014). "Treg may also promote fibrogenesis through TGF-β, IL-1 by inhibiting the recruitment of fibrocytes via the CXCL12/CXCR4 axis in a mouse model of acute lung injury." (PMID 36403186, 2023). "Our studies and those of our peers have shown that CXCL12 expression is markedly increased in the DRG after neuropathic pain induced by nerve injury or a chemotherapeutic agent and that inhibiting CXCR4, a CXCL12 receptor, attenuates these abnormal pain behaviours." (PMID 33658516, 2021). "Upon coupling with CXCR4, CXCL12 has been shown to lead to rapid and sustained mechanical allodynia and thermal hypersensitivity through inflammatory cytokine up-regulation in the spinal cord after nerve injury." (PMID 27760212, 2016). "After brain injury, CCL-23 and CXCL-12 modulate immune response through promoting migration of monocytes to the local sites of injury." (PMID 36315566, 2022).
metastatic carcinoma (15 papers, 2010 to 2025). A carcinoma which has spread from the original site of growth to another anatomic site. "Recently, CXCR4 was discovered to be a biomarker for NSCLC bone metastasis and presumably expression of this receptor facilitates homing to the CXCL12 expressing bone marrow as observed in other metastatic cancers." (PMID 29930538, 2018). "CXCL12 is secreted by several cell types within the bone marrow including OCLs and endothelial cells and this expression is well established in mediating osteotropism of several metastatic cancers." (PMID 29930538, 2018). "CXCL12/CXCR4 has also been shown to play a key role in the regulation of metastasis, and its expression has been shown to be elevated in localized and metastatic cancer, including bone metastatic prostate tumors." (PMID 23902739, 2013). "In diseases where excessive CXCR4 signaling exacerbates pathology, such as certain inflammatory and metastatic cancers, targeting GPR15LG could attenuate CXCL12-driven responses." (PMID 40394646, 2025). "The expression of CXCL12, CXCR4 and CXCR7 is elevated in CRC and tissue samples from lung metastasis, while the expression of both CXCL12 and CXCR7 is significantly higher in tissue samples derived from metastatic cancer in comparison to primary lesions." (PMID 34071492, 2021). "We compared the expression differences between metastatic cancer and primary cancer and found that, apart from a significant downregulation of CXCL14 and CCL28, as well as a significant upregulation of CXCL12 and CCL2, the expression levels of most chemokines did not achieve a twofold change." (PMID 39409185, 2024).